ABCC11 (ATP binding cassette subfamily C member 11)
Description:
ATP-dependent transporter of the ATP-binding cassette (ABC) family that actively extrudes physiological compounds and xenobiotics from cells. Plays a role in physiological processes involving bile acids, conjugated steroids and cyclic nucleotides, including cAMP and cGMP. Mediates the ATP-dependent efflux of a range of physiological lipophilic anions, including the glutathione S-conjugates leukotriene C4 and dinitrophenyl S-glutathione, steroid sulfates, such as dehydroepiandrosterone 3-sulfate (DHEAS) and estrone 3-sulfate, glucuronides such as estradiol 17-beta-D-glucuronide (E(2)17betaG), the monoanionic bile acids glycocholate and taurocholate, and methotrexate. Plays a role in the transport of earwax components. Participates in the secretion of odorants and their precursors from the apocrine sweat glands, including the secretion of glutamine conjugates, as well as the Cys-Gly-(S) conjugates of 3-methyl-3-sulfanyl-hexanol. Involved in the cellular extrusion of nucleotide analogs, hence confering resistance to various drugs, including clinically relevant drugs such as 5-fluorouracil (5-FU) and methotrexate.
Synonyms: MRP8; EWWD; WW
Tractability: Small molecule: it belongs to a druggable protein family. Antibody: UniProt places it where antibodies can reach, with high confidence; its Gene Ontology location is reachable by antibodies, with high confidence; UniProt predicts a signal peptide or a membrane-spanning region.
Target class: ABCC subfamily; ATP-binding cassette; Transporter; Primary active transporter
Safety:
Unwanted effects reported when the protein is acted on. In parentheses: how it was acted on, where the effect was seen, and who reports it.
leukopenia (source: ClinPGx)
Gene: Protein-coding gene on chromosome 16 (48,165,773 to 48,247,568, reverse strand). Ensembl gene ENSG00000121270.
Subcellular location: Cell membrane; Vacuole membrane; Cytoplasmic vesicle membrane; Apical cell membrane
Pathways (Reactome):
Transport of small molecules: ABC-family protein mediated transport
Gene Ontology:
Molecular function: ABC-type 3',5'-cyclic GMP transmembrane transporter activity; ABC-type bile acid transporter activity; ABC-type glutathione S-conjugate transporter activity; ABC-type xenobiotic transporter activity; purine nucleotide transmembrane transporter activity; transmembrane transporter activity; ATPase-coupled transmembrane transporter activity; ABC-type transporter activity; ATP binding; ATP hydrolysis activity
Biological process: bile acid and bile salt transport; leukotriene transport; purine nucleotide transport; transmembrane transport; xenobiotic transport; guanine nucleotide transmembrane transport
Cellular component: apical plasma membrane; cytoplasmic vesicle membrane; extracellular exosome; plasma membrane; vacuolar membrane; membrane
Genetic constraint (gnomAD): Loss-of-function variants: 130 observed, 149.78 expected, observed/expected ratio (o/e) 0.87, 90% interval 0.75 to 1. The upper end of that interval is the gene's LOEUF score, 1, which puts it in group 4 of 6, group 1 being the genes least tolerant of losing a copy. Missense variants: 1,636 observed, 1,759.4 expected, observed/expected ratio (o/e) 0.93, 90% interval 0.89 to 0.97. Synonymous variants: 645 observed, 686.26 expected, observed/expected ratio (o/e) 0.94, 90% interval 0.88 to 1.
Homologues: Orthologues: chimpanzee ABCC11 (97% identical), macaque ABCC11 (92% identical), dog ABCC11 (75% identical), rabbit ABCC11 (73% identical), pig ABCC11 (70% identical), Drosophila melanogaster MRP (30% identical), zebrafish abcc6b.2 (30% identical), zebrafish abcc6a (30% identical), Caenorhabditis elegans mrp-7 (29% identical), tropical clawed frog abcc2 (29% identical), zebrafish abcc10 (28% identical), Drosophila melanogaster CG31793 (28% identical), and 12 more. Paralogues in human: ABCC12 (47% identical), ABCC5 (40% identical), ABCC3 (31% identical), ABCC4 (30% identical), ABCC1 (30% identical), ABCC2 (29% identical), ABCC6 (29% identical), ABCC9 (28% identical), ABCC10 (27% identical), ABCC8 (27% identical), CFTR (25% identical).
Diseases named in the same sentence as ABCC11 in open-access papers:
ABCC11 is named in the same sentence as 34 diseases in open-access papers, as found by Europe PMC text mining. Sharing a sentence is not in itself a finding about the gene and the disease. The quoted sentences say what the papers report.
breast carcinoma (22 papers, 2008 to 2025). "Higher ABCC11 gene expression was also associated with poor response to NACT in breast cancer patients." (PMID 33334016, 2020). "It is reported that ABCC11 is highly expressed in aggressive breast cancer subtypes and is associated with poor prognosis." (PMID 30072632, 2018). "For the purpose of fast genetic diagnosis of AO and potential risk of breast cancer, specific primers were developed that allow to clinically genotype the ABCC11 gene within 30 minutes." (PMID 29180914, 2017). "The odds ratio for the women with genotypes (G/G + G/A) to develop breast cancer was estimated as 1.63 (p-value = 0.026), suggesting that the 538G allele in the ABCC11 gene is moderately associated with the risk of breast cancer." (PMID 23316210, 2012). "In this review article, we have addressed the potential impact of ABCC11 538G>A on the apocrine phenotype, patients’ response to nucleoside-based chemotherapy, and the potential risk of breast cancer." (PMID 21182469, 2010). "The odds ratio for the genotypes (G/G + G/A) in developing breast cancer was estimated as 1.63 (p-value = 0.026), suggesting that the G allele in the ABCC11 gene is moderately associated with the risk of breast cancer." (PMID 21182469, 2010). "Among such human ABC transporters, in this review article we will address human ABCC11 to discuss the potential impact of its genetic polymorphisms on the physiological function, breast cancer risk, and patients’ response to nucleoside-based chemotherapy." (PMID 21182469, 2010). "Further clinical studies, including protein expression studies in tumors, will be needed to clarify the potential contribution of ABCC11 to breast cancer risk and prognosis, including drug resistance and chemosensitivity." (PMID 21182469, 2010). "On the other hand, the wild type (Gly180) of ABCC11 is associated with wettype earwax, axillary osmidrosis, colostrum secretion from the mammary gland, and the potential susceptibility of breast cancer." (PMID 21182469, 2010). "Similar differences were observed for the breast cancer risk gene ABCC11 (1.8 in East Asians compared to 0.5 in Africans), as well as the multi-drug resistance genes ABCB1 (1.4 in South Asians compared to 0.2 in Africans) and ABCG2 (1.3 in East Asians compared to 0.1 in Europeans)." (PMID 32206879, 2020). "ABCC11 has also been implicated in aggressive breast cancer and prognosis." (PMID 33081264, 2020). "rs17822931 is in gene ABCC11, which is reported to be associated with breast cancer." (PMID 30072632, 2018). "Recently, a clinical method was developed to rapidly detect the genetic polymorphism (SNP 538G_A) in the ABCC11 gene by a SmartAmp method in ≈ 30 min which not only enables fast diagnosis of AO but also potential risk of breast cancer genetically related to both wet earwax type and AO." (PMID 29180914, 2017). "At the present time, it is not well understood whether ABCC11 WT really contributes to breast cancer risk." (PMID 21182469, 2010). "The expression of ABCC11 has been linked to aggressive TNBC- and HER2-enriched breast cancer subtypes and, thus, poor prognosis in a microarray-based study involving 281 Japanese patients." (PMID 33801148, 2021). "In breast cancer, ABCC11 overexpression has been observed in tumors with a highly aggressive molecular subtype." (PMID 34650973, 2021). "ABCC11 expression (together with ABCB1) is responsible for resistant phenotype of breast cancer cell lines resistant to eribulin and inhibition of ABCC11 can partially restore the cross-resistance to 5-fluorouracil." (PMID 33334016, 2020). "Further, ABCC1 and ABCG2 are highly expressed in core basal subtype, which is one of the most aggressive breast cancer subtypes, while ABCC11 is highly expressed in the HER2 or core basal subtypes." (PMID 28912626, 2017).
breast carcinoma (continued). "Other reports showed that ABCC1, ABCC11 and ABCG2 are highly over-expressed in subtypes of aggressive breast cancer and that increased expressions of ABCC1 and ABCC11 were significantly associated with shorter disease-free survival." (PMID 26883574, 2016). "Based on this result, we examined the expression of ABCB1 and ABCC11 in seven breast cancer cell lines and their eribulin-resistant cells by real-time RT-PCR and western blotting." (PMID 27588398, 2016). "In the present study, increased ABCC11 expression was detected in all of the eribulin-resistant clones established by exposing seven different breast cancer cell lines to eribulin." (PMID 27588398, 2016). "It has recently been reported that ABCC11 is potentially involved in drug resistance of breast cancer." (PMID 21182469, 2010). "ABCC11 is regulated by ERα, which mediates the tumour promoting effects of estrogens in breast cancer." (PMID 18837980, 2008). "Importantly, previous studies have already reported KCNK5 and ABCC11 as prognostic signatures in breast cancer." (PMID 39834541, 2024). "Our results suggest that ABCB1 and ABCC11 may be used as biomarkers for predicting the response to eribulin in patients with breast cancer." (PMID 27588398, 2016). "To confirm that both ABCB1 and ABCC11 were able to confer resistance to eribulin in breast cancer cells, we tested whether transient overexpression of ABCB1 or ABCC11 would alter the sensitivity to eribulin in HEK293T cells." (PMID 27588398, 2016). "To further examine the involvement of ABCB1 and ABCC11 in the development of eribulin resistance in breast cancer cells, we tested whether knockdown of ABCB1 or ABCC11 would restore eribulin sensitivity in eribulin-resistant breast cancer cells." (PMID 27588398, 2016). "High levels of ABCC11 mRNA were observed in breast cancer tissues." (PMID 23316210, 2012). "The potential involvement of ABCC11 in drug resistance of breast cancer has recently been reported." (PMID 23316210, 2012). "It remains to be elucidated whether the expression of ABCC11 WT (538G) is related to drug resistance of breast cancer and high rates of mortality." (PMID 23316210, 2012). "The aim of this work was to determine whether a DEX treatment may lead to any change in the expression level of ABCC11 protein in MCF7 breast cancer cells, an endocrine-related cell model." (PMID 22332017, 2011). "ABCC11 transcripts were overexpressed in estrogen receptor-(ER-) positive breast cancers." (PMID 22332017, 2011). "It is of great interest to investigate whether the expression of ABCC11 WT (538G) is related to drug resistance of breast cancer and high rates of mortality." (PMID 21182469, 2010). "The increased expression of ABCC11 wild type (WT) in breast cancer might be related with low levels of efficacy of chemotherapy, as discussed later in this review." (PMID 21182469, 2010). "Thus, ABCB1 and ABCC11 expression may be used as a biomarker for predicting the response to eribulin in patients with breast cancer." (PMID 27588398, 2016). "We initially thought that some genetically determined variation(s) in the apocrine system might influence susceptibility to breast cancer, although the genetic determinant (538G > A SNP in ABCC11) was not known at that time." (PMID 23316210, 2012). "Among the members of the ATP-binding cassette (ABC) transporter superfamily, MRP8/ABCC11 (MultiDrug Resistance Protein 8) is a full-length ABC transporter associated with resistance to methotrexate and fluoropyrimidines, two classes of agents widely used for breast cancer treatments." (PMID 22332017, 2011). "In particular, eribulin induced an acquired resistance in breast cancer cells by inducing an overexpression of ABCB1 and ABCC11 genes." (PMID 38534323, 2024).
breast carcinoma (continued). "In particular, multidrug-resistant protein-1 (ABCC1/MRP1), breast cancer resistance protein (ABCG2/BCRP) and multidrug-resistant protein-8 (ABCC11/MRP8) were expressed significantly more, and more frequently in TNBC compared to other breast cancer subtypes." (PMID 31443516, 2019). "The roles of ATP-binding cassette transporters, such as ABCC1, ABCC11, and ABCG2, in breast cancer patients have been reported." (PMID 28912626, 2017). "In the present study, we demonstrated that the expression of two ABC transporters, ABCB1 and ABCC11, which belong to different ABC transporter subfamilies, was increased in eribulin-resistant breast cancer cell lines." (PMID 27588398, 2016). "Particularly melanoma, carcinoma and solid tumors have the most significant enrichment of these genes, including ABCC11 (melanoma drug resistance), SNRNP200 (retinitis pigmentosa), TRERF1 (breast cancer) and WTX (Wilms tumor gene on X chromosome, Wilms tumor)." (PMID 25523808, 2014). "• The ABCC11 [ABC-binding cassette, subfamily C, member 11] gene product is highly expressed in breast cancer compared to normal tissue." (PMID 18837980, 2008). "In the present study, we demonstrated for the first time that ABCB1 and ABCC11 confer eribulin resistance in breast cancer cells regardless of their subtype." (PMID 27588398, 2016). "In the present study, upregulation of both ABCB1 and ABCC11 was observed in all seven breast cancer cell lines, regardless of their receptor status." (PMID 27588398, 2016). "Our data suggest that both ABCB1 and ABCC11 are involved in the development of eribulin resistance in breast cancer cells and that eribulin or its metabolites might be substrates of ABCB1 and ABCC11." (PMID 27588398, 2016). "Both ABCB1 and ABCC11 are involved in the development of eribulin resistance in breast cancer cells in vitro regardless of the breast cancer subtype." (PMID 27588398, 2016). "Hence, upregulation of both ABCB1 and ABCC11 in breast cancer cells was induced by continuous treatment regardless of the subtype of the cells." (PMID 27588398, 2016). "In conclusion, our study demonstrated that both ABCB1 and ABCC11 were able to confer resistance to eribulin; we also showed that increased expression of both ABCB1 and ABCC11 may be involved in the development of eribulin resistance in breast cancer cells, regardless of the subtype." (PMID 27588398, 2016). "ABCC11 mRNA and protein levels were enhanced by DEX (dexamethasone) and by PROG (progesterone) in MCF7 (progesterone receptor-(PR-) positive) but not in MDA-MB-231 (PR-negative) breast cancer cells." (PMID 22332017, 2011).
breast tumors (5 papers, 2010 to 2024). "Previously, we described that ABCC11 high levels are associated to the estrogen receptor (ER) expression level in breast tumors and in cell lines resistant to tamoxifen." (PMID 23641929, 2013). "Taken altogether, the association between PR and ABCC11, in a subgroup of breast tumors with low expression of ER, highlighted how ABCC11 might constitute a putative marker of 5-FU anticancer resistance." (PMID 22332017, 2011). "Furthermore, ABCC11 levels were positively correlated with the PR status of postmenopausal patient breast tumors from two independent cohorts." (PMID 22332017, 2011). "High expression levels of ABCC11 in PR-positive breast tumors with low expression of ER alpha may contribute to a decreased sensitivity to chemotherapeutic combinations containing 5-FU." (PMID 22332017, 2011). "The capability of STGIC is validated indirectly by expression of marker genes of invasive breast tumor in the predicted spatial domains, which are C6orf141, PDE5A, LINC00645, BMERB1, ABCC11, ABCC12." (PMID 38416785, 2024). "Furthermore, ABCC11 is overexpressed in estrogen receptor-positive cell lines resistant to tamoxifen and in ERBB2-overexpressing breast tumors." (PMID 23641929, 2013). "Thus, in the subclass of breast tumors (Estrogen Receptor-(ER-) negative/PR-positive), the elevated expression level of ABCC11 may alter the sensitivity to ABCC11 anticancer substrates, especially under treatment combinations with DEX." (PMID 22332017, 2011).
lung carcinoma (4 papers, 2012 to 2024). "In lung cancer cell lines, ABCC11 has been reported to confer resistance to fluorouracil, methotrexate, and pemetrexed." (PMID 27588398, 2016).
melanoma (2 papers, 2014 to 2023). A malignant, usually aggressive tumor composed of atypical, neoplastic melanocytes. "For example, PRSS12 in Panc-AdenoCA, ABCC11 in liver hepatocellular carcinoma (Liver-HCC), and NOD2 in skin melanomas (Skin-Melanoma) show tissue-specific expression patterns." (PMID 38143269, 2023).
cardiac hypertrophy (1 paper, 2015). "Three of them (ABCC4, ABCC5, and ABCC11) are expressed in cardiac tissue but ABCC4 is the most studied and has been shown to enhance cAMP formation, contractility, and cardiac hypertrophy." (PMID 26483685, 2015). "Three of them (MRP4 aka ABCC4, MRP5 aka ABCC5, and MRP8 aka ABCC11) have the ability to actively extrude cAMP and cGMP from the cell and in cardiac myocytes, MRP4 has been shown to enhance cAMP formation, contractility, and cardiac hypertrophy." (PMID 26483685, 2015).
cholesteatoma (1 paper, 2025). A pathologic process characterized by the proliferation of keratinizing squamous epithelium resulting in the accumulation of keratin and cells in the middle ear and/or mastoid. "In other words, alterations in the ear canal microbiota owing to ABCC11 gene polymorphisms may alter the microenvironment along with its metabolites, thereby potentially contributing to the development of otitis media pearls as a mechanism in the pathogenesis of cholesteatoma." (PMID 39817749, 2025).
chronic lymphocytic leukemia (1 paper, 2024). "ABCC11 is considered a drug efflux pump for nucleotide analogs, although, ABCC11 can be associated with fluoropyrimidine resistance in chronic lymphocytic leukemia." (PMID 38731966, 2024).
colorectal cancer (1 paper, 2024). A primary or metastatic malignant neoplasm that affects the colon or rectum. "Although it has not been seen to predict for PCa survival previously, ABCC11 has shown predictive ability in recurrence of colorectal cancer." (PMID 39352906, 2024).
Hyperglycemia (1 paper, 2016). An increased concentration of glucose in the blood. "Namely, chronic hyperglycemia might exacerbate axillary osmidrosis via the increase of matured ABCC11, since the current study implies that high levels of glucose would enhance the glycosylation of ABCC11, resulting in the increase in ABCC11 protein levels." (PMID 27281343, 2016).
leukopenia (1 paper, 2025). "For instance, ABCB1 rs1045642 and ABCC11 rs7194667 have been associated with an increased risk of fluoropyrimidine-induced adverse events, including diarrhea, mucositis, and leukopenia." (PMID 40428413, 2025).
malaria (1 paper, 2007). Malaria is a serious and sometimes fatal disease caused by a parasite that commonly infects a certain type of mosquito which feeds on humans. "Among regions with strong signatures of selection, we observed overlaps with genes that previously had been reported to be targets of strong selection such as DARC (FY) (YRI (test) vs. CEU) and ABCC11 (EAS vs. YRI/CEU) that are associated with malaria resistance and earwax type, respectively." (PMID 17356696, 2007).
middle ear cholesteatoma (1 paper, 2025). "It has been reported that the ABCC11 gene polymorphisms 538GG and 538GA are risk factors for middle ear cholesteatoma." (PMID 39817749, 2025).
ovarian carcinoma (1 paper, 2017). A malignant neoplasm originating from the surface ovarian epithelium. "Finally, ABCC11 and ABCG2 have also been detected in ovarian cancers; the ABCG2 as a marker of side-populations of ovarian cancer cells that show stem-cell characteristics." (PMID 28674494, 2017).